TMPRSS2 (transmembrane serine protease 2)
Diseases named in the same sentence as TMPRSS2 in open-access papers (continued):
Sharing a sentence is not in itself a finding about the gene and the disease.
prostate carcinoma (continued). "PCSD1 xenograft tumors were characterized as PSA+, AR+, K5-, K14-, K8+, K18+, AMACR+, NKX3.1+, and TMPRSS2:ERG- human prostate cancer." (PMID 22035283, 2011). "The recent discoveries of the TMPRSS2-ERG rearrangement in subset of prostate cancer, with prevalence between 40–70% of all tumors, raised the question of the presence of this genetic aberration in more aggressive forms of prostate tumors." (PMID 22110988, 2011). "This discovery provides novel insights into the role of TMPRSS2/ERG in prostate cancer progression and describes a new mechanism for PIM1 regulation mediated by the ERG DNA binding domain." (PMID 22140532, 2011). "The TMPRSS2-ERG fusion is known to be prevalent in prostate cancer, with the predominant isoform being e1-e4, which we found in our reads." (PMID 21261984, 2011). "TMPRSS2-ERG fusions alter prostate cancer progression by promoting cell invasion, activating C-MYC oncogene and abrogating prostate epithelial differentiation." (PMID 21731703, 2011). "Their results underlined that the prior knowledge about the TMPRSS2-ERG fusion status will help to identify more accurate biomarkers and to develop novel targeted therapy strategies for prostate cancer in the future." (PMID 22142399, 2011). "It is well understood that driver gene fusions are typically found to be recurrent, such as BCR-ABL, ETV6-NTRK3, and TMPRSS2-ERG in prostate cancer, and consequently they are ideal targets for therapeutic intervention." (PMID 22032724, 2011). "AR plays a crucial role in prostate cancer progression and is known to regulate the TMPRSS2 promoter, which constitutes the regulatory part of the TMPRSS2/ERG fusion." (PMID 21747944, 2011). "The TMPRSS2-ERG fusion gene is a frequent genomic rearrangement in prostate cancers that results in placing the ERG ETS-family transcription factor under the androgen-regulated expression of the TMPRSS2 gene." (PMID 22035283, 2011). "Our results demonstrate that the TMPRSS2-ERG gene fusion leads to transcriptional modulation, which is associated with widely accepted prostate cancer biomarkers and signaling pathways." (PMID 22142399, 2011). "Several studies demonstrated that compared to PIN lesions, TMPRSS2/ERG rearrangement frequency in localized invasive prostate cancers, is doubled." (PMID 21747944, 2011). "A common genetic alteration in prostate cancer is a signature gene fusion between the androgen-regulated TMPRSS2 and the transformation-specific (ETS) transcription factor family members." (PMID 21731703, 2011). "While a significant amount of investigations have been done on the tumor biological functions of TMPRSS2 fusion-driven ETS overexpression in prostate cancer, few papers have reported on its potential downstream targets." (PMID 21731703, 2011). "ERG and ETV1 are overexpressed in prostate cancer, but they also fuse with TMPRSS2, which leads to tumor progression." (PMID 24213111, 2011). "Although TMPRSS2-ERG fusion seems to be a critical event in prostate cancer, the precise functional role in cancer development and progression is still unclear." (PMID 22142399, 2011). "Recently, a frequent chromosomal aberration fusing androgen regulated TMPRSS2 promoter and the ERG gene (TMPRSS2/ERG) was discovered in prostate cancer." (PMID 21747944, 2011). "Meanwhile, the TMPRSS2-ERG translocation, which has been found to occur with regular frequency in prostate carcinomas, appears to be associated with HDAC expression and is thus linked with sensitivity to HDAC inhibitors." (PMID 21285985, 2011). "Studies found that approximately 50% of prostate cancers harbor TMPRSS2-ERG fusions, of which greater than 90% over-express ERG." (PMID 21731703, 2011). "The main motivation of this study is therefore to unravel such TMPRSS2/ERG related pathways in the context of prostate cancer." (PMID 21747944, 2011).
prostate carcinoma (continued). "Fusions of TMPRSS2 and three other genes encoding ETS transcription factors, ETV1, ETV4 and ETV5, which are located on different chromosomes, occur at low frequency in prostate cancer." (PMID 21298110, 2011). "Androgen stimulation can increase expression of the TMPRSS2-ERG fusion in fusion positive prostate cancer cells." (PMID 21731703, 2011). "In 2005 the most frequent genetic alteration involving ERG was found in prostate cancer (PCa), where the 5′-untrascribed region of the prostate-specific and androgen-responsive TMPRSS2 gene is fused to ERG in approximately 50% of PCa cases." (PMID 22140532, 2011). "Several studies suggest that TMPRSS2:ERG fusion prostate cancer contribute to a more aggressive cancer phenotype, which is associated with higher tumor stage and prostate cancer-specific death." (PMID 24281166, 2010). "Numerous studies have now confirmed that approximately 50% of prostate cancers harbor a recurrent fusion between TMPRSS2 and ERG or ETV1." (PMID 20964841, 2010). "Our objective is to present recent findings on the application of PCA3 and TMPRSS2:ERG in prostate cancer diagnosis and management." (PMID 24281166, 2010). "To identify markers associated with TMPRSS2–ERG fusion and prognostic of biochemical recurrence, we analysed a cohort of 139 men with prostate cancer for 502 molecular markers." (PMID 20068566, 2010). "A preliminary investigation of TMPRSS2:ERG mRNA transcript levels in blood specimens of prostate cancer patients has been reported." (PMID 20598135, 2010). "It should be noted that the prevalence of TMPRSS2:ERG gene fusions in prostate cancer is 44-50% in serum PSA-screened cohorts and 15-36% in population-based cohorts." (PMID 20598135, 2010). "Comparison of PSA, PCA3 and TMPRSS2:ERG mRNA copy levels in CTC enriched fractions from androgen-dependent prostate cancer patients." (PMID 20598135, 2010). "Comparison of PSA, PCA3 and TMPRSS2:ERG mRNA copy levels in CTC enriched fractions from androgen-independent prostate cancer patients." (PMID 20598135, 2010). "The previously identified TMPRSS2–ERG T1/E4 gene fusion represents a potentially important factor in prostate cancer progression, the prognostic value of which has yet to be fully defined." (PMID 20068566, 2010). "In summary, we have identified androgen related gene TMPRSS2 that is regulated by SREBF1, PBX1 and ETS family members that are associated with the prostate cancer and gene TMPRSS2 has been found in 80% of tumor experiments." (PMID 20025723, 2009). "One of these has been shown to be overexpressed in PCa-PCA-3 and the other is a product of a chromosomal rearrangement, which creates a common prostate cancer-specific product, the TMPRSS2:ERG fusion." (PMID 19401683, 2009). "Recently, fusions between genes encoding ETS transcription factors and genes encoding prostate-specific genes, mostly TMPRSS2-ERG, have been reported as most frequent genetic alteration in early stages of human prostate cancer." (PMID 19461893, 2009). "This included two leukemia cell lines, RCH-ACV and REH, known to carry the TCF3:PBX1 and ETV6:RUNX1 fusion genes, respectively, and four prostate cancer samples positive for the TMPRSS2:ERG fusion gene." (PMID 19152679, 2009). "For prostate cancer sample P140, the expected TMPRSS2 exon 1:ERG exon 4 fusion gene was assigned a fusion score rank of 95 within the 10,297 fusion breakpoints (and number one within the 154 measured junctions of TMPRSS2:ERG)." (PMID 19152679, 2009). "Recently, fusion of the prostate-specific androgen-regulated TMPRSS2 gene to the ETS family transcription factor gene ERG was reported as a common event in prostate cancer." (PMID 18594527, 2008). "Several studies have focused on elucidating the role of the TMPRSS2-ERG gene fusion in prostate cancer." (PMID 18694509, 2008). "There is considerable interest in the relationship between the TMPRSS2-ERG gene fusion and prostate cancer risk." (PMID 18694509, 2008).
prostate carcinoma (continued). "The presence of the TMPRSS2-ERG fusion gene in prostate tumors has recently been associated with an aggressive phenotype, as well as recurrence and death from prostate cancer." (PMID 18694509, 2008). "In this study, fluorescent in situ hybridization (FISH) assays were used to assess TMPRSS2-ERG fusion status in a group of 214 prostate cancer cases from two population-based studies." (PMID 18694509, 2008). "Prostate cancer-specific survival was evaluated for the 214 cases scored for the TMPRSS2-ERG fusion and these results are summarized in Kaplan-Meier plots." (PMID 18694509, 2008). "If the association between the TMPRSS2 SNP and fusion type is replicated and in particular, if other SNPs associated with the acquisition of this gene fusion are identified, these data may present opportunities to augment or further current prostate cancer diagnostic abilities." (PMID 18694509, 2008). "Demographic and clinical characteristics of prostate cancer patients by tumor TMPRSS2-ERG gene fusion status." (PMID 18694509, 2008). "In particular, duplication of the TMPRSS2–ERG fusion has been shown to identify aggressive tumours in patients whose prostate cancers had been assigned only intermediate Gleason scores." (PMID 19002168, 2008). "The presence of TMPRSS2 fusion with ERG in prostate cancer samples was examined by RT–PCR of RNA for all cases." (PMID 17971772, 2007). "The potential utility of the TMPRSS2:ERG fusion product as an independent prognostic marker for patients with clinically localised prostate cancer remains controversial." (PMID 17971772, 2007). "The prostate-specific gene, TMPRSS2 is fused with the gene for the transcription factor ERG in a large proportion of human prostate cancers." (PMID 17971772, 2007). "Among prostate cancer patients treated with surgery, the expression of TMPRSS2:ERG fusion gene is a strong prognostic factor and is independent of grade, stage and PSA level." (PMID 17971772, 2007). "Notably, SPOP-mutant prostate cancers are mutually exclusive with TMPRSS2-ERG fusions and enriched for Wnt pathway alterations." (PMID 40432836, 2025). "TMPRSS2–ERG gene fusion may induce tumor invasion, metastasis, and angiogenesis in prostate cancer through gene mutation or immune regulation." (PMID 40145441, 2025). "Through the immunohistochemical analysis of autopsy specimens, we demonstrate a significant reduction in pulmonary TMPRSS2 expression in ADT-treated patients compared to untreated prostate cancer patients and controls, with direct AR antagonists showing particularly potent suppressive effects." (PMID 41150771, 2025). "Interestingly, androgen deprivation therapy decreases the expression of TMPRSS2 and reduces the risk of SARS-CoV2 infection in prostate cancer patients." (PMID 41375068, 2025). "TMPRSS2 expression is up-regulated in response to androgens in prostate cancer." (PMID 41408854, 2025). "For instance, the discovery of Transmembrane Protease, Serine 2 gene (TMPRSS2) with the erythroblast R transformation gene (ERG) (TMPRSS2-ERG) fusions in over 50% of prostate cancers has enabled the stratification of patients and prediction of response to androgen deprivation therapies." (PMID 40565559, 2025). "Many prostate cancers carry a translocation leading to the TMPRSS2::ERG oncoprotein leading to amplified ERG levels which could potentially be detected by FLI1 1.2." (PMID 41283512, 2025). "Moreover, the aberrant expression of ERG resulting from the TMPRSS2-ERG fusion is closely associated with increased cell proliferation, neovascularization, and invasive behavior in prostate cancer." (PMID 39963114, 2025). "Its increased expression in prostate cancer indicates that TMPRSS2 might be a therapeutic target for prostate cancer." (PMID 41408854, 2025).
prostate carcinoma (continued). "The present study was designed to determine whether ADT modulates TMPRSS2 expression in the lung tissue of prostate cancer patients and to assess whether specific ADT regimens differ in their effects on pulmonary TMPRSS2 levels." (PMID 41150771, 2025). "Looking specifically at AR-associated gene expression in our treatment-naïve primary prostate cancer samples, our AIPC cohort demonstrates significantly lower expression of AR, FOXA1, TMPRSS2, KLK3, AZGP1, and several other AR-associated genes when compared with the non-AIPC cohort." (PMID 39859392, 2025). "Previous studies reported that prostate cancers harboring TMPRSS2-ERG fusions are more dependent on androgen signaling and may be more responsive to androgen deprivation therapy." (PMID 40711866, 2025). "The authors further demonstrated that TMPRSS2 inhibition by hepatocyte growth factor activator inhibitor-2 abrogates the TMPRSS2-induced invasion of the prostate cancer cells and that activated matriptase levels correlate with TMPRSS2 expression in LNCaP and VCaP prostate cancer cells." (PMID 40214422, 2025). "Prostate cancer exhibits even more pronounced racial variations: Black men show higher frequencies of SPOP and ZFHX3 mutations but lower rates of TMPRSS2‐ERG fusions and PTEN deletions compared to White men, while Asian men demonstrate increased FOXA1 mutations and fewer PTEN alterations." (PMID 41187942, 2025). "Moreover, it has been previously reported that TMPRSS2 proteolytic activity is crucial for prostate cancer metastasis." (PMID 40214422, 2025). "If molecular changes characteristic of prostate cancer, such as structural alterations in the TMPRSS2 and ERG genes, can be identified, histopathological evaluation could be conducted independently." (PMID 40565112, 2025). "TMPRSS2‐ERG fusion is a relatively common event seen in prostate cancer." (PMID 38379333, 2024). "The existence of TMPRSS2:ERG in prostate cancer, along with the significant modulation of TMPRSS2 by androgens, has led to the speculation that the male predominance in the COVID-19 pandemic may be partly attributed to TMPRSS2." (PMID 38793660, 2024). "FBXO45 was identified as a prognostic biomarker in TMPRSS2-ERG-positive prostate cancer." (PMID 38773471, 2024). "An observational study of prostate cancer patients demonstrated that prostate carcinoma containing the TMPRSS2‐ERG fusion gene may respond to E2 signalling." (PMID 38923119, 2024). "Similar to the effects of quercetin in Calu‐3‐ALIs and PBECs, a mixture containing quercetin downregulated TMPRSS2 and other androgen‐responsive genes in prostate cancer cells, and quercetin acts as an antagonist of estrogen receptor‐mediated activities in HeLa cells." (PMID 38886986, 2024). "Indeed, TMPRSS2 was initially identified in prostate cancer and TMPRSS2 was shown to be strongly upregulated in response to androgens in prostate cancer cell lines." (PMID 37047226, 2023). "The inhibition of p300 has been shown to reduce the proliferation of prostate cancer cells with TMPRSS2:ETS (E26 transformation-specific) fusions, and combining p300 inhibitors with other targeted therapies may increase their efficacy." (PMID 37511059, 2023). "Prostate cancers with the TMPRSS2-ERG gene fusion account for 40 to 80% of total cases." (PMID 36672280, 2023). "Given the scarcity of high-quality research pertaining to this issue, our ability to draw firm conclusions and uncover substantial findings regarding the potential clinical application of TMPRSS2 and p300 in the management of prostate cancer patients is influenced by bias." (PMID 37511059, 2023). "TMPRSS2-ERG gene fusions can diagnose prostate cancer on a molecular level." (PMID 37021836, 2023). "More recent studies showed that viruses linked to respiratory infections, including SARS-CoV-2, need the TMPRSS2-ERG complex to enter cells, and it has been discussed if prostate cancer patients are more exposed to these infections due to TMPRSS2-ERG overexpression." (PMID 37021836, 2023).
prostate carcinoma (continued). "Interestingly, TMPRSS2 is a key regulator in prostate cancer (PCa) progression which is regulated by androgen receptor (AR) signaling." (PMID 36834705, 2023). "Furthermore, we plan to develop a similar approach toward other gene fusions, such as ROS1, RET, and NTRK in NSCLC, but also gene fusions identified in other solid cancers, such as TMPRSS2-ERG in prostate cancer, EVT6-NTRK3 in secretory breast carcinoma etc." (PMID 37016288, 2023). "TMPRSS2–ERG had an independent, additional predictive value compared to PCA3 and the ERSPC (The European Randomized Study of Screening for Prostate Cancer) risk calculator parameters with respect to the prediction of a biopsy’s Gleason score and clinical tumor stage." (PMID 36672713, 2023). "Furthermore, it is worth noting that TMPRSS2-ERG fusion transcripts are frequently described in prostate cancer." (PMID 37896901, 2023). "TMPRSS2–ERG fusion is recognised as a driver event for the progression to prostate cancer." (PMID 36980776, 2023). "Tumors that express TMPRSS2-ERG gene fusions are considered fusion-positive prostate cancers." (PMID 37021836, 2023). "However, it is questionable if the presence of a TMPRSS2‐ERG fusion constitutes a predictive biomarker: Nearly 50% of prostate cancers lack TMPRSS2‐ERG." (PMID 39188554, 2023). "TMPRSS2 is also central to prostate cancer metastasis and constitutes a target for treatment." (PMID 37660915, 2023). "In human prostate cancer, TMPRSS2::ERG (T2E) is the most commonly observed oncofusion." (PMID 37509339, 2023). "In recent years, TMPRSS2:ERG has been a major focus of research in the field of prostate cancer." (PMID 36980776, 2023). "Also, it is obtained that most of the studied genes (TMPRSS2, ERG, ETV5 and AR) are associated with pathways involved in the development of prostate cancer." (PMID 37287057, 2023). "Shallow deletion accounted for the second most genetic alterations of TMPRSS2 in prostate cancer while most alterations did not account for mutation." (PMID 36239108, 2022). "It is mutually exclusive with other alterations including SPOP and CHD1 loss of function, indicating that TMPRSS2‐ERG negative prostate cancers progress by different tumorigenic processes or represent different cellular subtypes." (PMID 35347810, 2022). "In addition to viral infection, TMPRSS2 is a potential target for cancer therapy with well-documented links to prostate cancer metastasis, where a TMPRSS2–ERG fusion gene is found in 50% of prostate tumours." (PMID 36293378, 2022). "Furthermore, authors revealed such genes for the TMPRSS2-ERG prostate cancer molecular subtype (B4GALNT4, ASRGL1, MYBPC1, RGS11, SLC6A14, GALNT13 and ST6GALNAC1)." (PMID 36077746, 2022). "In prostate cancer cells, TMPRSS2 is strongly upregulated in response to androgens." (PMID 35712238, 2022). "Recurrent fusions at the TMPRSS2 5′ UTR (untranslated region) to ETV1 (ETS variant transcription factor 1) or ERG (ETS-related gene) lead to outlier expression and drive progression of prostate cancer." (PMID 36364238, 2022). "TMPRSS2-ERG gene rearrangement, the most common E26 transformation specific (ETS) gene fusion within prostate cancer, is known to contribute to the pathogenesis of this disease and carries diagnostic annotations for prostate cancer patients clinically." (PMID 35513774, 2022). "Furthermore, compared to the most frequently detected TMPRSS2-ERG form (e1e4), e2e4 encodes 31 more amino acids and accelerated neuroendocrine process of prostate cancer." (PMID 36088396, 2022). "TMPRSS2 is commonly expressed in prostate cancer (PCa) cells and is regulated by androgens." (PMID 35657341, 2022). "The pivotal role of TMPRSS2 in the progression of prostate cancer is widely studied." (PMID 35558557, 2022).